RTN3 (reticulon 3)
Description:
May be involved in membrane trafficking in the early secretory pathway. Inhibits BACE1 activity and amyloid precursor protein processing. May induce caspase-8 cascade and apoptosis. May favor BCL2 translocation to the mitochondria upon endoplasmic reticulum stress. Induces the formation of endoplasmic reticulum tubules. Also acts as an inflammation-resolving regulator by interacting with both TRIM25 and RIGI, subsequently impairing RIGI 'Lys-63'-linked polyubiquitination leading to IRF3 and NF-kappa-B inhibition. (Microbial infection) Plays a positive role in viral replication and pathogenesis of enteroviruses.
Synonyms: HAP; NSPLII; ASYIP; NSPL2; RTN3-A1
Tractability: Antibody: its Gene Ontology location is reachable by antibodies, with high confidence. PROTAC: ubiquitination databases record sites on it; its protein half-life has been measured.
Gene: Protein-coding gene on chromosome 11 (63,681,446 to 63,759,909, forward strand). Ensembl gene ENSG00000133318.
Subcellular location: Endoplasmic reticulum membrane; Golgi apparatus membrane
Subcellular location (Human Protein Atlas): Endoplasmic reticulum
Pathways (Reactome):
Disease: Dengue Virus Genome Translation and Replication
Neuronal System: Synaptic adhesion-like molecules
Gene Ontology:
Molecular function: protein binding
Biological process: endoplasmic reticulum tubular network formation; endoplasmic reticulum tubular network organization; negative regulation of amyloid-beta formation; reticulophagy; brain development; endoplasmic reticulum tubular network membrane organization; neuron differentiation
Cellular component: endoplasmic reticulum; endoplasmic reticulum membrane; Golgi apparatus; Golgi membrane; extracellular region; neuron projection; plasma membrane; postsynaptic density; synapse
Genetic constraint (gnomAD): Loss-of-function variants: 39 observed, 71.53 expected, observed/expected ratio (o/e) 0.55, 90% interval 0.42 to 0.71. The upper end of that interval is the gene's LOEUF score, 0.71, which puts it in group 2 of 6, group 1 being the genes least tolerant of losing a copy. Missense variants: 1,186 observed, 1,221 expected, observed/expected ratio (o/e) 0.97, 90% interval 0.93 to 1.02. Synonymous variants: 440 observed, 451.57 expected, observed/expected ratio (o/e) 0.97, 90% interval 0.9 to 1.05.
Homologues: Orthologues: chimpanzee RTN3 (99% identical), macaque RTN3 (81% identical), dog RTN3 (78% identical), rabbit RTN3 (73% identical), mouse Rtn3 (67% identical), rat Rtn3 (64% identical), guinea pig Rtn3 (23% identical), tropical clawed frog rtn3 (23% identical), Drosophila melanogaster Rtnl1 (15% identical), zebrafish rtn3 (15% identical), Drosophila melanogaster Rtnl2 (7% identical). Paralogues in human: RTN4 (21% identical), RTN1 (18% identical), RTN2 (12% identical), PRR18 (3% identical).
Diseases named in the same sentence as RTN3 in open-access papers:
RTN3 is named in the same sentence as 64 diseases in open-access papers, as found by Europe PMC text mining. Sharing a sentence is not in itself a finding about the gene and the disease. The quoted sentences say what the papers report.
Alzheimer disease (22 papers, 2012 to 2026). A progressive, neurodegenerative disease characterized by loss of function and death of nerve cells in several areas of the brain leading to loss of cognitive function such as memory and language. "RTN3 deficiency has been implicated in Alzheimer's disease (AD) 44, and decreased TEX264 expression has been observed in AD-associated neuroinflammation." (PMID 40959274, 2025). "Rtn3 is associated with the pathological processes of Alzheimer's disease (AD), regulating nerve cell function and biological processes associated with certain neurodegenerative diseases." (PMID 38745725, 2024). "The relevance of RTN3 in Alzheimer’s disease is also underlined by a study that found multiple RTN3 variants in patients with sporadic early and late onset of this disease." (PMID 35188422, 2022). "RINDs were abundantly present in a mouse model of Alzheimer’s disease (AD) and hence RTN3 overexpression has been implicated in causing hippocampal age-dependent RINDs." (PMID 34440784, 2021). "Mutations in RTN3 have been detected in early‐onset Alzheimer's disease." (PMID 36925557, 2023). "Moreover, RTN3 variants have been identified in patients with sporadic early- and late-onset Alzheimer’s disease, even if a direct correlation with the role of RTN3 in ER-phagy remains to be determined." (PMID 32154249, 2020). "The deficiency of RTN3 located in the endoplasmic reticulum increases the activity of BACE1 and promotes amyloid deposition in a mouse model of Alzheimer's disease; RTN3 thus showed its neuroprotective effect." (PMID 41578884, 2026). "Extensive research has focused on the role of RTN3 in Alzheimer’s disease, where transgenic mice overexpressing RTN3 show neuroinflammatory abnormalities." (PMID 37575244, 2023). "RTN3 has a role in synaptic plasticity and synapse formation, and its role in regulating the neuropathology of Alzheimer’s disease (AD) has been reported." (PMID 35331286, 2022). "The relevance of ER-phagy on neuronal homeostasis is further suggested by RTN3 involvement in the etiology of neurodegenerative Alzheimer’s disease." (PMID 32154249, 2020). "Our data suggest that RTN3 has a stronger association with Alzheimer’s disease (AD) pathology than RTN1, and this difference is likely related to unique sequences that are present in RTN1 and RTN3 as well as their differential localizations in neruites." (PMID 28733667, 2017). "A few RTN3 variants were also identified in Alzheimer's disease; however, authors did not pay attention to patients’ blood pressure." (PMID 38352050, 2024). "Interestingly, RTN3-immunoreactive dystrophic neurites have been found in Alzheimer’s disease brains, and DCTN6 deficiency enhanced RTN3 protein level and the formation of RTN3-immunoreactive dystrophic neurites in the hippocampus of aging mice." (PMID 36879021, 2023). "The role of RTN3 in Alzheimer’s disease (AD) has been widely investigated." (PMID 28717245, 2017). "Reticulon 3 (RTN3), a protein predominantly expressed in the brain and localized in the ER, is known to be involved in Alzheimer’s disease, likely by inhibiting β-secretase enzyme 1 (BACE1), which cleaves amyloid precursor protein." (PMID 24710477, 2012).
viral infection (5 papers, 2016 to 2025). "Beyond supporting replication, RTN3 has also been linked to the exosome-mediated phase of viral infection." (PMID 41012666, 2025). "Subsequently, RTN3 is upregulated in an ER stress- and/or inflammation-dependent manner, which is directly associated with acute viral infection." (PMID 34313226, 2021). "Therefore, viral infection status may serve as a key determinant of the role of RTN3 in HCC, although the exact underlying mechanisms still require further investigation." (PMID 37575244, 2023). "Collectively, depressed RTN3 expression facilitates antiviral innate immune and inflammatory responses upon viral infection." (PMID 34313226, 2021). "Based on previous studies, it is hypothesized that the role of RTN3 in HCC is likely influenced by the viral infection status of patients with HCC." (PMID 37575244, 2023). "However, the mechanism and function of RTN3 upregulation during viral infection is unclear, raising the strong possibility that RTN3 is involved in antiviral and inflammatory responses." (PMID 34313226, 2021). "To further elucidate the physiological function of RTN3 in antiviral responses, we depleted its expression by short hairpin RNAs (shRNAs) in human healthy donor PBMCs, in which RTN3 normally undergoes upregulation during viral infection." (PMID 34313226, 2021). "A potential mechanism for RTN3 induction may be ER stress upon acute viral infection." (PMID 34313226, 2021). "The results showed that RTN3 interacted with TRIM25 under basal conditions and was slightly strengthened upon viral infection." (PMID 34313226, 2021). "By identifying RTN3 and its functional domains as critical for packaging DENV RNA into EVs, we address a long-standing knowledge gap in extracellular vesicle biology during viral infection." (PMID 41012666, 2025). "We next assessed whether RTN3 is upregulated and inhibits RIG-I-mediated innate immune antiviral responses in vivo during viral infection by treating C57BL/6 mice with PBS, poly(I:C) or VSV-eGFP separately via intravenous (I.V.)injection." (PMID 34313226, 2021).
prion disease (4 papers, 2017 to 2020). A transmissible disease that is caused by a protein that is able to induce abnormal folding of normal cellular proteins, leading to characteristic spongiform brain changes, which are associated with neuronal loss without an inflammatory response. "Moreover, in mice with early-stage prion disease, cooling-associated suppression of elongation via phosphorylation of eEF2K correlated with increased expression of the synaptic protein reticulon 3 (RTN3), which was shown to be neuroprotective." (PMID 32298235, 2020). "We next asked to what extent RTN3 is neuroprotective in mice with neurodegenerative disease, using mice with prion disease, specifically tg37 mice inoculated with Rocky Mountain Laboratory (RML) strain as in our previous studies." (PMID 28238655, 2017).
chronic kidney disease (3 papers, 2022 to 2025). Impairment of the renal function secondary to chronic kidney damage persisting for three or more months. "We also found that RTN3 deficiency can lead to chronic kidney disease and aggravate cisplatin induced acute kidney injury." (PMID 39972424, 2025). "A protein (RTN3) known to be involved in neurodegenerative diseases may play a causative role in kidney fibrosis or scarring, and chronic kidney disease (CKD)." (PMID 35596061, 2022). "As an endoplasmic reticulum (ER) protein, Reticulum 3 (RTN3) has been reported to play a crucial role in neurodegenerative diseases, lipid metabolism, and chronic kidney disease." (PMID 39972424, 2025). "The aim of the present study was to clarify the roles of RTN3 in chronic kidney disease (CKD) and kidney fibrosis." (PMID 35596061, 2022). "In the RTN3 KO mouse model, we also found that deletion of RTN3 can activate the IGF2–Janus kinase 2 (JAK2) pathway, which may further lead to chronic kidney disease and renal fibrosis." (PMID 36925557, 2023).
heart failure (3 papers, 2024 to 2025). Inability of the heart to pump blood at an adequate rate to meet tissue metabolic requirements. "Moreover, Reticulon 3 deficiency ameliorates post-myocardial infarction heart failure in myocardial infarction mice." (PMID 39177670, 2024). "Elevated RTN3 has been reported in the myocardium of patients with heart failure after myocardial infarction." (PMID 39177670, 2024).
hepatocellular carcinoma (3 papers, 2017 to 2024). A malignant tumor that arises from hepatocytes. "In conclusion, we identified a three-gene predictive signature comprised of UPB1, SOCS2 and RTN3 for hepatocellular carcinoma and validated these three genes expression pattern in HCC tissues." (PMID 28717245, 2017).
malaria (3 papers, 2012 to 2014). Malaria is a serious and sometimes fatal disease caused by a parasite that commonly infects a certain type of mosquito which feeds on humans. "The levels of reticulon 3 (RTN3) is significantly increased in malaria and other infections suggesting that it may be linked to the disease." (PMID 24934404, 2014). "It is of interest that RTN3 expression has been repeatedly associated with neurodegenerative diseases in humans and that RTN3 is differentially expressed in brains of experimental malaria resistant and susceptible strains of mice infected with Plasmodium berghei ANKA." (PMID 23144702, 2012). "This study suggests that the protective effect of the sickle cell trait may be linked to the raised level of Transforming Growth Factor beta and provides additional support for a role of ABO and RTN3 against severe malaria." (PMID 24934404, 2014). "This study suggests that the protective effect of the sickle cell trait may be linked to the raised level of TGF-ß and provides additional support for a role of ABO and RTN3 against severe malaria." (PMID 24934404, 2014).
Obesity (3 papers, 2022 to 2024). Accumulation of substantial excess body fat. "RTN3 has been identified in the mouse brain, kidney, liver, lung, testis, and ovary, especially the brain, and its aberrant expression is associated with obesity, hypertriglyceridemia (HTG), chronic kidney disease, and hepatocellular carcinogenesis." (PMID 38352050, 2024). "Our previous study revealed that overexpressed RTN3 is associated with obesity and HTG, which are connected with hypertension." (PMID 38352050, 2024). "We have reported that RTN3 overexpression is associated with HTG and obesity, which are important factors for secondary hypertension." (PMID 38352050, 2024). "Another study on obesity revealed that RTN3 binds to HSPA5 (also called GRP78), which regulates SREBP‐1c activation and promotes lipid synthesis." (PMID 38420163, 2024). "For these high‐RTN3‐expression patients but without obesity and HTG, we thought that it may be caused by individual differences, environments, dietary habits, and/or life styles." (PMID 38352050, 2024). "These discoveries suggested the association between high expression of RTN3 and hypertension and that this linkage may be independent of obesity and HTG." (PMID 38352050, 2024). "To further investigate the association between RTN3 and hypertension, we enrolled 18 healthy controls and 56 primary hypertension patients with normal triglyceride levels (<1.7 mmol/L) and body mass index (18.5–24 kg/m2) to exclude the effects of HTG and obesity." (PMID 38352050, 2024). "Exceeding our estimation, the increased expression of RTN3 was also detected in subjects with primary hypertension but without obesity and HTG." (PMID 38352050, 2024). "Our previous study reported that overexpression of RTN3 may partly lead to HTG and obesity, which are important factors in the development of secondary hypertension." (PMID 38352050, 2024). "In addition, Ang II‐induced hypertensive mice without obesity and HTG also appeared increased RTN3." (PMID 38352050, 2024).
amyloid (2 papers, 2017 to 2021). "More interestingly, RTN3 is abundantly enriched in dystrophic neurites that surround amyloid plaques found in the brains of AD patients and AD mouse models." (PMID 28733667, 2017).
astrocytoma (2 papers, 2017 to 2018). "Moreover, studies performed in cancer tissues from patients point toward an oncogenic role of RTN3, as it was shown that increased RTN3 levels are observed in astrocytoma whereas no expression was observed in healthy glial cells." (PMID 30250843, 2018).
lung fibrosis (2 papers, 2025). "Here, we found that RTN3 deficiency may contribute pulmonary fibrosis via reducing the antifibrotic ER-anchored CRTH2 and promoting CRTH2 regulated profibrotic macrophage differentiation." (PMID 39972424, 2025). "Our findings shed light on the importance of the relationship between RTN3 and pulmonary fibrosis in humans and animals, and indicated that RTN3 may be a novel pulmonary fibrosis-causing gene." (PMID 39972424, 2025). "Our study first builds the relationship between RTN3 and pulmonary fibrosis, and the RTN3 may be a novel pulmonary fibrosis-causing gene." (PMID 39972424, 2025). "Thus, our research suggests that RTN3 may play a crucial role in pulmonary fibrosis and the reduction of RTN3 in the lungs could be a risk factor for pulmonary fibrosis." (PMID 39972424, 2025). "We may first report loss-of-function mutations of RTN3 in patients with pulmonary fibrosis." (PMID 39972424, 2025). "To confirm the relationship between RTN3 and lung fibrosis in human population, we enrolled 124 patients with ILD." (PMID 39972424, 2025). "RTN3-null mice exhibited more severe pulmonary fibrosis phenotypes in old age or after bleomycin treatment." (PMID 39972424, 2025). "The involvement of RTN3 in idiopathic pulmonary fibrosis (IPF), a progressive and fatal interstitial lung disease, remains unexplored." (PMID 39972424, 2025). "The HE staining and Masson staining revealed that compared to bleomycin induced Wild type mice, the RTN3-null mice showed more serious pulmonary fibrosis symptoms after bleomycin treatment." (PMID 39972424, 2025). "IHC analysis of lung tissues also found that the higher the severity of pulmonary fibrosis, the lower the expression of RTN3 was." (PMID 39972424, 2025). "In this study, we explored the role of RTN3 in pulmonary fibrosis using public datasets, IPF patient samples, and animal models." (PMID 39972424, 2025). "To investigate the relationship between RTN3 and pulmonary fibrosis, we first analyzed RTN3 RNA levels in IPF patients from public databases." (PMID 39972424, 2025). "IHC and Western blot analysis of mouse lung tissue showed that the higher the severity of lung fibrosis (the longer the duration of bleomycin use), the lower the expression of RTN3." (PMID 39972424, 2025). "The RTN3-null mice presented more severe pulmonary fibrosis at old age or after bleomycin treatment." (PMID 39972424, 2025). "To elucidate the relationship between RTN3 reduction and pulmonary fibrosis, we performed mRNA sequencing of lung tissue from 16-month-old RTN3-null and 16-month-old WT mice." (PMID 39972424, 2025). "The identification of these mutations in RTN3 further confirmed the relationship among RTN3, CRTH2 and lung fibrosis." (PMID 39972424, 2025). "Our study first builds the relationship between RTN3 gene and pulmonary fibrosis." (PMID 39972424, 2025). "Both effects of RTN3 reducing in lung fibroblasts and alveolar macrophages promote lung fibrosis." (PMID 39972424, 2025). "This study showed a strong correlation between reduced RTN3 levels and pulmonary fibrosis." (PMID 39972424, 2025). "In summary, our study suggested that decreased RTN3 can aggravate age or bleomycin induced pulmonary fibrosis by increasing the collagen deposition, partly through reducing the antifibrotic ER-anchored CRTH2 and promoting CRTH2 regulated profibrotic macrophage differentiation." (PMID 39972424, 2025). "The effects of RTN3 and CRTH2 in lung fibroblasts and alveolar macrophages aggravated age or bleomycin induced pulmonary fibrosis." (PMID 39972424, 2025). "Western blot analysis of the lung tissues found that the levels of pulmonary fibrosis markers including α-SMA, p-Smad3 and Fn1 were higher in RTN3-null group than in Wild type group after bleomycin treatment." (PMID 39972424, 2025).
lung fibrosis (continued). "Western blot analysis of MRC5 further confirmed that the longer the duration of TGFβ treatment, the higher the expression of lung fibrosis markers (including COL1A1 and Vim), but the lower the expression of RTN3." (PMID 39972424, 2025). "Both effects of RTN3 and CRTH2 in lung fibroblasts and alveolar macrophages aggravated age-or bleomycin-induced pulmonary fibrosis." (PMID 39972424, 2025). "Additionally, at 16 months of age, the RTN3-null mice (n = 6) developed pulmonary fibrosis without any treatment, whereas the wild-type mice of the same age did not exhibit such fibrosis." (PMID 39972424, 2025). "In this study, we obtained clinical and genetic evidence that the lack of RTN3 in lung fibroblasts and alveolar macrophages may contribute to pulmonary fibrosis." (PMID 39972424, 2025).
memory impairment (2 papers, 2024). "Thus, artificially manipulating the miR-dDiAs/RTN3 signals replicated the DG-CA3 circuit and memory impairments seen in isolated AD mice." (PMID 38011644, 2024).